LAG3 (lymphocyte activating 3)
Diseases named in the same sentence as LAG3 in open-access papers (continued):
Sharing a sentence is not in itself a finding about the gene and the disease.
tumor (continued). "Tumour-infiltrating lymphocytes (TILs) exhibit elevated expression of exhaustion markers such as PDCD1, LAG3, and HAVCR2, accompanied by reduced effector cytokines, reflecting chronic antigen exposure." (PMID 41179304, 2025). "Immunophenotyping of murine spleens showed that this delay in disease was accompanied by more tumor-reactive CD8+ T cells that coexpressed fewer inhibitory receptors (e.g., PD-1, LAG-3, and TIM-3)." (PMID 40742099, 2025). "The identification of additional co‐inhibitory receptors, including emerging immune checkpoints like LAG‐3, TIM‐3 and TIGIT, is advancing anti‐tumour immunotherapy development." (PMID 40415479, 2025). "Combining LAG3 inhibitors with MWA significantly promoted the proliferation and antitumor function of CD8+ TILs, delaying tumor progression and extending survival in an MC38 tumor model." (PMID 41002563, 2025). "Exhausted T cells upregulate multiple inhibitory receptors (IRs), including PD-1, CTLA-4, TIM-3, LAG-3, and TIGIT, which bind to ligands on tumor cells and antigen-presenting cells (APCs), impeding T cell survival, expansion, and function." (PMID 40475782, 2025). "Together, these findings imply that LAG-3 blockade, especially in combination with PD-1 or PD-L1, has significant potential for overcoming CSC-mediated immune evasion and enhancing anti-tumor immune responses." (PMID 41233805, 2025). "However, therapies targeting T cells (such as those which act on the PD1, LAG3 or TIGIT pathways) have yielded limited success in OC so far suggesting that other immune cells or other pathways might play a pivotal role in this type of tumor." (PMID 40464605, 2025). "Tumor-reactive T cells in the tumor microenvironment show an exhausted phenotype, expressing inhibitory cell surface markers such as PD1, LAG-3, and TIM-3." (PMID 40519933, 2025). "While the harvested tumor had SLL deposits, it resulted in a CD8+ predominant, tumor-reactive TIL product with an increased expression of LAG-3 and TIGIT." (PMID 41333460, 2025). "While CD8+ T cells are critical for anti-tumor immunity, they often become dysfunctional in the TME and express the exhaustion markers LAG3 and TOX." (PMID 41194931, 2025). "In vitro pre‐activated T cells share main characteristics of antigen‐experienced T cells within the tumor microenvironment, such as upregulation of exhaustion markers PD‐1, TIM‐3, LAG‐3, and CTLA‐4 as well as enhanced IL‐12Rβ1 expression." (PMID 39981925, 2025). "CD8+ T cells that exhibited high expression levels of exhaustion gene (HAVCR2, ENTPD1, LAG3, PDCD1, CXCL13, TOX, and GZMB) in the primary tumor were extracted and clustered." (PMID 40364834, 2025). "The mitochondria-targeted drug Met attenuates upregulation of the immune checkpoints programmed cell death protein 1 (PD-1) and lymphocyte activation gene-3 (LAG-3), thereby increasing CD8+ T cell infiltration and survival in the harsh tumor microenvironment." (PMID 41246345, 2025). "Previous studies consistently reported that the expressions of LAG-3, PD-1, PD-L1, CD28, CD80, CD27 and CTLA-4 were relevant to the immunosuppression in the tumor microenvironment." (PMID 39781354, 2025). "In contrast to αKO tumor sections, p-αKO tumors displayed markedly elevated cell counts positive for PD1, CTLA4, and LAG3." (PMID 40067762, 2025). "In tumor‐infiltrating CD8+ T cells, cholesterol content in tumor tissues is positively correlated with the upregulation of immune checkpoint markers such as PD‐1, 2B4, TIM‐3, and LAG‐3." (PMID 40145543, 2025). "When correlating tumor expression with RFS, higher LAG-3 and CD8 expression in resected tumors enriched for RFS benefit in both the nivolumab plus relatlimab and nivolumab arms." (PMID 41109920, 2025). "Composite indices were generated to quantify immune suppression (PD-L1, PD-1, LAG3, FOXP3, IDO, CD68), CAF activation (SMA, Vimentin), endothelial activation (CD31), and tumor proliferation (Ki67)." (PMID 41595458, 2025).
tumor (continued). "We found minimal expression of PD1, LAG3, and CTLA4 on both CB- and AD-8F4CAR-iNK T cells suggesting unimpaired anti-tumor function." (PMID 40519924, 2025). "In one study of tumor samples from resected HCC patients, the expression of LAG-3 on TILs was found in 65% of samples along with expression of PD-L1 in 83%." (PMID 40076561, 2025). "The co-inhibitory receptors LAG-3, PD-1, and TIM-3 were expressed by significantly higher proportions of CD4+ and CD8+ T lymphocytes in tumor tissue and ascites compared to peripheral blood." (PMID 40649775, 2025). "Our work revealed that LAG3, TIM3, and CTLA4 are crucial ICPs on iNKT cells favoring immune escape and tumor progression." (PMID 41562072, 2025). "Activated NK cells express various T-cell immune checkpoint molecules like PD-1, CTLA-4, LAG3, and TIM3, which can inhibit their tumor-fighting functions." (PMID 41425568, 2025). "Here, we observed elevated co-expression of PD-1 with TIGIT, TIM-3, LAG-3, and NKG2A, which was particularly pronounced in tumor-infiltrating CD8+ T cells compared to peripheral blood." (PMID 41300994, 2025). "CD137 (4-1BB), a potential immunotherapy target, regulates PD-1, LAG-3, and TIM-3 expression in tumor-infiltrating Tex cells." (PMID 41194917, 2025). "Studies have shown that LAG-3 is upregulated on T cells within the TME of GBM, contributing to immune evasion and suppression of anti-tumor responses." (PMID 40223940, 2025). "In the same way, we observe an increased LAG-3 expression in peripheral CD8+ T cells of patients with CC compared with HD, elevated levels were detected within the tumor microenvironment." (PMID 41300994, 2025). "Tumor‐infiltrating CD8+ T cells exhibited reduced exhaustion markers (CD39, LAG‐3 under YD monotherapy) and increased proliferation/activation (Ki‐67 and CD25)." (PMID 40108893, 2025). "Acquired resistance, on the other hand, can develop during treatment due to adaptive immune evasion, such as upregulation of alternative immune checkpoints (e.g., LAG-3, TIGIT) or depletion of effector T cells in the tumor microenvironment." (PMID 40299523, 2025). "We injected CT26, 4T1 and B16F10 MMRd or MMRp cell lines in mice and used anti-TIM3/TIGIT/LAG3/CTLA4 alone or in combination with anti-PD-1, 14 days following tumor inoculation." (PMID 40027748, 2025). "Under the long-term stimulation of tumor antigens, some tumor-infiltrating lymphocytes will up-regulate the expression of some immunosuppressive receptors, such as PD-1, TIM3, LAG-3, and TIGIT." (PMID 40612858, 2025). "Previous researches have revealed that programmed cell death ligand (PD-L1) is highly expressed in GTN tumor tissue, and other immune targets TIM-3, LAG-3, and GAL-9 are also widely expressed in GTN." (PMID 38166849, 2024). "It primarily functions by blocking the interactions between PD-1 and its ligands PD-L1 and PD-L2, as well as LAG3 and MHC-II, thereby restoring T cell functionality and enhancing anti-tumor responses." (PMID 39743998, 2024). "Other ligands, including fibrinogen-like protein 1 (FGL1), galectin-3 (Gal-3), and liver sinusoidal endothelial cell lectin (LSECtin), have been identified to bind with LAG-3, thereby suppressing CD8-mediated anti-tumor responses." (PMID 38785789, 2024). "Targeting immune checkpoints such as PD-L1, TIM-3, or LAG-3 with ICIs in HCC can reverse the exhausted state of infiltrating T cells within the TME, thereby enabling them to exert their anti-tumor functions." (PMID 39146202, 2024). "In this study, we characterized dynamic changes in CD8+ TPEX after four chemotherapies in four murine tumor models and identified ICB targets (anti-PD-1/anti-LAG-3) to combine with chemotherapy." (PMID 39343508, 2024).
tumor (continued). "On the other hand, CD4 + and CD8 + T cells trigger tumour escape by expressing immune checkpoint molecules (PD-1, LAG-3, CTLA-4, TIM-3) that bind to their related ligands on DCs and/or tumours, thereby stopping an immune reaction." (PMID 39720956, 2024). "Lymphocyte activation gene 3 (LAG3) is an inhibitory receptor and the interaction between fibrinogen-like protein 1 and LAG3 can inhibit the anti-tumor effect of T cells both in vivo and in vitro, which was regarded as a new immune evasion mechanism." (PMID 39453075, 2024). "In stage I-III CRC, an increased tumor TIM3 and LAG3 expression correlated with a decreased OS, while an increased expression on immune cells had the opposite effect." (PMID 39199569, 2024). "Important checkpoints in CRC are lymphocyte-activation gene 3 (LAG3), CTLA4, T-cell immunoglobulin and mucin-domain containing-3 (TIM-3) and PDL1, which control tumor growth and progression." (PMID 39080202, 2024). "Tumor cells that secrete VEGF upregulate immune-suppressive molecules such as CTLA4, LAG3, and TIM3." (PMID 38540240, 2024). "ZGGS15, a novel IgG4 BsAb that targets LAG-3 and TIGIT, has demonstrated exceptional anti-tumor efficacy by inhibiting LAG-3 and TIGIT." (PMID 38724599, 2024). "Despite activating receptors on the target enhance NK cell-mediated tumor lysis, expression of ligands on tumors to inhibitory NK receptors, such as NKG2A, TIGIT and LAG3, can induce NK cell exhaustion and suppress their anti-tumor function." (PMID 39415291, 2024). "The abundant expression of ICOS, LAG3, OX40, PD-1, and TIM3 at the tumor margin indicates active participation of T cells in the immune response to tumor cells, which can lead to T cell depletion." (PMID 39845973, 2024). "al. also showed that the overexpression of LAG-3 in human primary HNSCC correlates with elevated pathological categories, massive tumor sizes, and pragmatic lymph node levels." (PMID 38474377, 2024). "Following coculture with CD33+ tumor cells, both CAR33 and DARIC33 T cells exhibited a similar activation profile; however, the CAR33 cells had higher expression of PD-1, LAG3, CD69, and CD25, suggesting greater activation following T cell activation." (PMID 38502193, 2024). "Slightly lower levels of T-cell immune inhibitory receptors PD-1, LAG-3, and TIM-3, proliferation, and GZMB were also observed in this patient’s tumor supporting reduced T-cell exhaustion/dysfunction during treatment." (PMID 39318388, 2024). "We demonstrate that a high abundance of TILs co-expressing PD1 with LAG3, TIGIT, or TIM3 within the tumor microenvironment predicts poorer ORRs, PFS, and OS in patients with NSCLC treated with ICIs, regardless of PD-L1 status." (PMID 39591972, 2024). "LAG-3 is usually overexpressed on TILs and OS analysis pinpoints that LAG-3 acts as a predictive element unaided by tumor size." (PMID 38474377, 2024). "Most of the CD8+ T cells in the tumor were CD45RAloCD27hi and expressed PD-1, TIM-3, CTLA-4, LAG-3, TIGIT, and CD39." (PMID 39273452, 2024). "Lymphocyte activation gene-3 (LAG-3) is a novel immunosuppressive receptor which is abnormally expressed in various TMEs, and is a substantial immune checkpoint molecule in tumor immune response." (PMID 39218939, 2024). "LAG-3, a key checkpoint receptor alongside PD-1 and CTLA-4, promotes tumor growth by inhibiting the immune response at high expression levels." (PMID 39769271, 2024). "In the univariate regression analysis, LAG3 expression, AJCC stage, tumor pathological stage (T), and the presence of metastasis (M) were all identified as significant prognostic risk factors for KIRC." (PMID 38277212, 2024). "LAG-3 binds to the MHC II complex on macrophages, TIM-3 binds to galectin-9 on tumor cells, TIGIT binds to CD155, and CD86 binds to CTLA-4." (PMID 39518937, 2024). "This increase in LAG-3 contributes to the depletion of T-cells in the TME and restricts the ability of T-cells to respond against the tumor." (PMID 38390331, 2024).
tumor (continued). "Currently, most clinical trials of LAG-3 inhibitors have focused on the combination of LAG-3 and PD-1, as this combination has been approved by the FDA and has shown encouraging results in clinical trials of multiple tumor types." (PMID 39252941, 2024). "Relatlimab, a humanized IgG4 monoclonal antibody developed by Bristol-Myers Squibb (BMS), targets LAG-3, inhibiting its interaction with MHC-II and thereby restoring T cell function to attack and eliminate tumor cells." (PMID 39743998, 2024). "Mice treated with anti-LAG-3 or anti-TIM-3 exhibited a more variable response to treatment, with the anti-TIM-3-treated group achieving a significant reduction in tumor burden (p = 0.0492)." (PMID 39623404, 2024). "Various studies have suggested that the markers of T‐cell exhaustion, such as CTLA‐4, BTLA, LAG‐3, 2B4, TIM‐3, CD160, and PD‐1, induce the functionally impaired state and thereby suppress the proliferation of the exhausted T cells in tumor tissues." (PMID 38204220, 2024). "LAG3 and TIGIT were more widely dispersed in the tumor location, and their expression levels rose with increasing distance from the tumor." (PMID 39256364, 2024). "LAG-3 and PD-1 are continuously co-expressed on TILs, and combined blockade of LAG-3 and PD-1 pathways has shown promise in improving the inhibitory tumor microenvironment." (PMID 38627681, 2024). "In particular, preclinical studies using mAbs to block LAG3 and PD1 inhibitory activity showed significant increases in tumor clearance and survival in several mouse tumor models." (PMID 38556085, 2024). "Mouse models demonstrated that combining LAG3 and PD1 inhibitors overcame tumor resistance to either agent alone." (PMID 39199569, 2024). "We report the generation of a novel anti-LAG-3/TIGIT bispecific IgG4 antibody, ZGGS15, and evaluated its anti-tumor efficacy in mouse models as monotherapy or in combination with a PD-1 antibody." (PMID 38724599, 2024). "In the tumor microenvironment, especially in tumor-infiltrating T cells, co-expression of TIM-3 and LAG-3 correlates with the exhaustion status of T cells." (PMID 38835341, 2024). "Both anti-LAG-3 and anti-PD-1 ICB with chemotherapy were required for the complete tumor regression observed." (PMID 39343508, 2024). "One of the most important features of ‘immune hot tumours’ is the activation of immune checkpoints including PD-1, CTLA-4, and lymphocyte activation gene 3 (LAG3)." (PMID 38461439, 2024). "These humanized monoclonal antibodies target inhibitory receptors (CTLA-4, PD-1, LAG-3, TIM-3) or ligands (PD-L1) expressed on T lymphocytes, antigen presenting cells, and tumor cells and elicit an anti-tumor response by stimulating the immune system." (PMID 40757683, 2024). "As for tumor samples, similar to the tDLNs and spleen we observed that CD19 + LAG-3 + comprised only a fraction of total B cells." (PMID 38773133, 2024). "By blocking the release of TGF-β1 from UPP1-overexpressing tumor cells using TGF-β1 neutralizing antibodies, we observed a marked decrease in the LAG3 + PDCD1+ exhausted T cell population." (PMID 38331898, 2024). "It has already been proven that anti PD-1 antibodies are able to halt PD-1 receptors and promote anti-tumor CD8+ T cell activity, but this is a new method in which LAG-3 itself is altered." (PMID 39796650, 2024). "When tested in vivo, T-cells expressing FGFR4.28HTM.28z-CD276.8HTM.BBz BiCisCAR exhibited faster tumor eradication, increased persistence, and reduced expression of exhaustion markers such as CD39, PD-1, and LAG-3." (PMID 39043633, 2024). "High grade tumors had a significantly higher infiltrate of FoxP3+ cells (p = 0.02), CD68+ cells (p = 0.01), CD163+ cells (p = 0.01), LAG3+ cells (p = 0.01), PD1+ cells (p = 0.01) and TIM3+ cells (p = 0.03) when compared with low grade tumours." (PMID 38691575, 2024). "Within the tumor microenvironment (TME), there is a notable upregulation of LAG-3 expression on the outer membrane of tumor-infiltrating lymphocytes (TIL)." (PMID 38390331, 2024).
tumor (continued). "ADAM10 clearly plays a critical role in not only regulating tumor cell intrinsic physiology but also shaping the GBM TME by affecting IC levels and expression as is the case with LAG-3." (PMID 39346924, 2024). "LAG3, often expresses on the lymphocytes, including CD4+ T cells, NK cells, CD8+ T cells, and Treg cells, impeding the tumor immune microenvironment through accelerating T cell exhaustion and blocking T cell proliferation." (PMID 39872538, 2024). "Some scholars also found that tumor-specific co-suppressor receptors (e.g., TIM3, LAG3, and TIGIT, etc.)are highly expressed in a subpopulation of tumor-infiltrating Tregs." (PMID 39329710, 2024). "NK/T cell subgroups in HNSCC group highly expressed marker genes of depleted T cells such as CTLA4, LAG3, TIGIT, HAVCR2, etc., indicating that tumor tissue was more sensitive to NK/T cells." (PMID 38582791, 2024). "Bavunalimab (XmAb841 or XmAb22841) is a bispecific anti-CTLA-4/LAG-3 antibody, which activated T cells in NSG mice to achieve anti-tumor effects." (PMID 39252941, 2024). "ZGGS15, a BsAb that blocks both LAG-3 and TIGIT, can potently inhibit LAG-3 and TIGIT receptors on immune cells by attaching to their specific binding ligands, MHC-II and PVR (CD155), on tumor cells." (PMID 38724599, 2024). "YY1 overexpression in anti-tumor CD8 T cells regulates immune evasion, in part through its transcriptional regulation of LAG-3." (PMID 39796650, 2024). "Accordingly, we demonstrated herein that NExT are naturally functionalized with diverse receptors (PD1, LAG3, TIM3) that can interact with their corresponding ligands (e.g., PDL1, Galectin-3, FGL-1, MHCII, Galectin-9, HMGB1, Ceacam-1) within the tumor." (PMID 38730475, 2024). "Further in vivo experimentation demonstrated that the injection of monoclonal antibodies (McAbs) targeting LAG-3, PD-1, and FGL-1 led to a modest inhibition of tumor growth." (PMID 39331884, 2024). "TIM-3 and LAG-3 were co-expressed with markers like PD-L1, B7H3, IDO-1, and VISTA, indicating a role in immune regulation within the tumor microenvironment." (PMID 39769271, 2024). "In PRAD, tumor-specific CD4+ and CD8+ T cells exhibit rapid upregulation of LAG-3 upon encountering antigens in vivo." (PMID 39120585, 2024). "The interaction between FGL1 and its receptor LAG-3 can result in the reduction of CD8+ tissue-resident memory T cells within tumors, facilitating immune evasion by the tumor." (PMID 38816776, 2024). "We found that it was correlated with tumor immunotherapy targets BTLA, CTLA4, HAVCR2, LAG3, PDCD1, and TIGIT in HNSC; ICOS were all significantly correlated." (PMID 39483471, 2024). "Preclinical studies have demonstrated upregulated expressions of LAG-3 or TIM-3 in immunotherapy-resistant tumors, whilst co-blockade of these checkpoint molecules augments tumor response to anti-CTLA-4 and anti-PD-1 immunotherapies." (PMID 38673829, 2024). "In contrast, the expression of ICPs was induced more rapidly in transferred cells as the expression of Lag-3 and Tim-3 was detectable starting from 3 days of presence in RMA-KR tumor-bearing mice." (PMID 39196934, 2024). "In a murine tumor model, FS-118 decreases LAG-3 expression on tumor-infiltrating lymphocytes (TILs) while raising sLAG-3 levels in mouse serum." (PMID 39252941, 2024). "To validate our findings, we examined the expression of activation (CD69, OX40) and exhaustion markers (LAG3, TIM3) markers on T cells in FFPE tissue sections from humanized EMC041 PDX tumours collected at sacrifice." (PMID 38711203, 2024). "ATRi treatment altered the activation status of tumor-infiltrating CD8 + T cells, resulting in downregulated expression of PD-1, LAG3, and Tim3, along with an increase in IFN-γ-secreting CD8 + T cells, thereby enhancing the cytotoxic activity of these cells." (PMID 39487895, 2024). "Its primary mechanism of action involves blocking the interaction between LAG3 and MHC-II molecules, thereby restoring T cell-mediated cytotoxicity against tumor cells." (PMID 39743998, 2024).